MT-ND4 (mitochondrially encoded NADH:ubiquinone oxidoreductase core subunit 4)
Diseases named in the same sentence as MT-ND4 in open-access papers (continued):
Sharing a sentence is not in itself a finding about the gene and the disease.
tumor (27 papers, 2007 to 2025). "In the whole mitochondrial genome sequencing study in GC, it has been reported that the tumor has remarkably more variants in the MT-ND4 region." (PMID 37482618, 2023). "OSCC cells exhibited strong upregulation of COX-2 and mitochondrial genes (MT-ND2, MT-ND4, MT-ND5, and cytochrome b), indicating increased metabolic activity, a hallmark of tumor progression." (PMID 40061903, 2025). "To study the role of CD8+ T (MT‐ND4) cells in tumor immunity and metastasis, we employed STRING to analyze protein interactions and Cytoscape to display the top 10 core genes." (PMID 38872260, 2024). "In this analysis, we observed a statistically significant difference between all groups, with tumor group presenting more heteroplasmic variants in MT-RNR1, MT-ND5, MT-ND4, MT-ND2, MT-DLOOP1 and MT-CO1." (PMID 31673122, 2019). "Tumor also presented substantially more variants in the following regions: MT-RNR1, MT-ND5, MT-ND4, MT-ND2, MT-DLOOP1 and MT-CO1." (PMID 31673122, 2019). "Further, the higher rate of heteroplasmic variants in tumor groups was statistically significant in six of such regions: MT-RNR1, MT-ND5, MT-ND4, MT-ND2, MT-DLOOP1 and MT-CO1." (PMID 31673122, 2019). "Interestingly, one of the tumour samples (T10) had several mutations in mtDNA: MT‐ND1, MT‐ND4 and MT‐ATP6." (PMID 37317665, 2023). "In this study, CD8+ T cells were subdivided into four sub‐clusters, NCF1, FGFBP2, MT‐ND4, and SPC25, all of which failed to destroy tumor cells, resulting in metastasis." (PMID 38872260, 2024).
mitochondrial disease (15 papers, 2013 to 2026). "Five lymphoblastoid cell lines derived from mitochondrial disease patients harboring point mutations in mtND1, mtND4, or mtATP6 were characterized in two high throughput assays assessing mitochondrial function." (PMID 29587845, 2018). "Mitochondrial deletions are typical of mitochondrial disease, therefore we examined whether mitochondrial deletions differed in ASD compared to controls by quantifying the copy number of the mitochondrial gene MT-ND1 relative to MT-ND4; the latter resides in the major mitochondrial deletion arc." (PMID 34381777, 2021).
cancer (14 papers, 2006 to 2025). A tumor composed of atypical neoplastic, often pleomorphic cells that invade other tissues. "In this study, our analyses with multiple types of cancer have highlighted different mtDNA mutations, particularly in the MT-ND4, MT-ND5 and D-loop, suggesting a special importance of such mitochondrial mutations and regions during cancer development and progression." (PMID 35183124, 2022). "The somatic variants identified in our cohort and those found in cancers of MITOMAP both showed enrichment on D-loop and MT-ND4, while our results were additionally enriched on MT-ND1 and MT-ND5." (PMID 38566210, 2024). "In fact, mutations in MT-ND4 and MT-ND5 leading to complex I dysfunction have been previously associated with procancerous phenotypes and tumorigenesis in different types of cancer, although the particularities of this relationship are still unknown." (PMID 35183124, 2022). "We also highlighted that most shared variants were in the MT-ND4, MT-ND5 and D-loop, and that some of these variants were nonsynonymous, indicating a special importance of these variants and regions regarding cancer progression, involving genomic and epigenomic alterations." (PMID 35183124, 2022). "Also among the upregulated genes were mitochondrial protein coding genes (MT-ND3, MT-ND4L, MT-ND4, MT-ND2, MT-CYB, MT-ND1, MT-CO1 etc), which may be as a result of the elevated metabolism characteristic of cancer cells to sustain their survival." (PMID 29132323, 2017).
neurodegenerative disease (3 papers, 2021 to 2023). A disorder of the central nervous system characterized by gradual and progressive loss of neural tissue and neurologic function. "Here, we found that the species of Mn can increase or arrest the expression of genes such as MT-CO1, MT-CYB, MT-ND4, and COX4I2, which are associated with glycolysis and glycogenesis, and oxidative phosphorylation, along with neurodegenerative diseases such as AD, HD, and PD." (PMID 34941782, 2021).
MT-ND4 also shares sentences with these, for which no sentence is quoted: optic atrophy (12 papers); Leigh syndrome (9); MELAS syndrome (8); hereditary optic neuropathy (5); infection (5); osteosarcoma (4); Parkinson disease (4); Alzheimer disease (3); glioblastoma (3); type 2 diabetes mellitus (3); acute myeloid leukaemia (2); asthenozoospermia (2); autosomal dominant optic atrophy (2); bipolar disorder (2); bladder cancer (2); cardiomyopathy (2); colon cancer (2); colorectal cancer (2); cystic fibrosis (2); Dengue (2); depression (2); Huntington disease (2); lactic acidosis (2); leprosy (2); lung carcinoma (2); metabolic disease (2); mitochondrial myopathies (2); oncocytoma (2); ovarian carcinoma (2); pancreatic cancer (2).
A further 80 diseases each share a sentence with MT-ND4 in 2 papers or fewer.